HPSE (heparanase)
Diseases named in the same sentence as HPSE in open-access papers (continued):
Sharing a sentence is not in itself a finding about the gene and the disease.
hypercoagulability (4 papers, 2014 to 2023). "Increasing evidence implicate Heparan sulfate proteoglycans (HSPGs) and Heparanase in various diseases and pathologies, including hypercoagulability states." (PMID 34132790, 2021). "Use of the assay as part of thrombophilia work-up and correlating results with newly identified heparanase polymorphisms are challenging areas requiring further investigation." (PMID 25386347, 2014).
ischemia (4 papers, 2016 to 2020). A hypoperfusion of the BLOOD through an organ or tissue caused by a PATHOLOGIC CONSTRICTION or obstruction of its BLOOD VESSELS, or an absence of BLOOD CIRCULATION. "Upregulation of HPSE in vascular cells, neurons, and astrocytes of mouse brain was reported 7 days post-ischemia." (PMID 33127645, 2020). "Activated macrophages secrete TNFα and cathepsin L, which stimulate further production and activation of heparanase by these cells and by ischemia-induced renal injured cells." (PMID 28388547, 2017). "It is not known if the role of HPSE in acute I/R also occurs in long term ischemia observed in CKD." (PMID 27467172, 2016).
membranous nephropathy (4 papers, 2012 to 2025). "The heparanase activity in granulocytes of patients with membranous nephropathy was also higher than heparanase activity in granulocytes in the control group (p = 0.02)." (PMID 27091112, 2017). "The heparanase activity in granulocytes of patients with lupus nephritis and membranous nephropathy was higher than heparanase activity in granulocytes in the control group (p = 0.02 in both cases)." (PMID 27091112, 2017). "The results of this study show the increase in heparanase activity in the granulocytes from patients with lupus nephritis and membranous nephropathy." (PMID 27091112, 2017). "A correlation between heparanase activity in granulocytes and serum total protein level (r = −0.69; p = 0.02) in membranous nephropathy was observed." (PMID 27091112, 2017). "Increase in heparanase activity without changes in superoxide dismutase activity in the granulocytes from patients with lupus nephritis and membranous nephropathy was observed." (PMID 27091112, 2017). "The observation that heparanase in granulocytes of the patients with membranous nephropathy is increased in comparison with healthy controls is enhanced by the negative correlation between granulocyte heparanase and total protein serum level." (PMID 27091112, 2017).
pancreatitis (4 papers, 2017 to 2023). Inflammation of the pancreas. "In order to reveal the significance of heparanase in pancreatitis, we applied a well-established cerulein-based mouse model." (PMID 28386074, 2017). "In pancreatitis, heparanase is expressed by pancreatic acinar cells and infiltrated cells or possibly centroacinar cells, in which heparanase partially co-localizes with cathepsin L (overlay, yellow)." (PMID 28386074, 2017).
Stroke (4 papers, 2017 to 2024). Sudden impairment of blood flow to a part of the brain due to occlusion or rupture of an artery to the brain. "HPSE expression in cerebral vessels increased after stroke onset and infarct volume greatly decreased after co-administration of N-acetylcysteine + glycosaminoglycan oligosaccharides as compared with N-acetylcysteine administration alone." (PMID 33127645, 2020). "Because HS level decreased in infarct lesions, scission activity of HPSE was measured, and it was found that HPSE activity was elevated 3 and 24 h after the stroke induction." (PMID 33127645, 2020). "The information concerning the role of heparanase in neuroinflammation during different types of strokes is limited." (PMID 28720149, 2017). "Additionally, upregulation of heparanase in vascular cells and astrocytes was found in a mouse model following stroke." (PMID 34573906, 2021). "The upregulation of heparanase, along with the degradation of HSPGs, may correspond to angiogenesis and tissue repair in the brain following stroke." (PMID 34573906, 2021). "Because HPSE protein levels increased in vascular cells 24 h post stroke induction, the impact of glycocalyx protection on the infarct volume was next examined using low-molecular-weight heparin (LMWH: enoxaparin) as an inhibitor of HPSE and low-molecular-weight CS (pLMWCS) as an HYAL1 inhibitor." (PMID 33127645, 2020). "Thus, expression levels of HPSE, MMP9, and HYAL1-4 in infarct lesions at 3 and 24 h after stroke onset were investigated using Western blotting." (PMID 33127645, 2020).
Thrombocytopenia (4 papers, 2020 to 2024). A reduction in the number of circulating thrombocytes. "Despite this, no heparanase inhibitors have been approved for clinical use as they are limited by cost, production complexity, and off target effects such as anticoagulant activity and thrombocytopenia resulting from their structural similarity to heparin." (PMID 38302978, 2024).
acute lymphoblastic leukemia (3 papers, 2012 to 2021). Leukemia with an acute onset, characterized by the presence of lymphoblasts in the bone marrow and the peripheral blood. "The SNP rs4693608 lies within an enhancer regulating the expression of HPSE, by affecting the self-regulation of the oncogenic transcription factor in acute lymphoblastic leukemia (ALL), with the A allele carriers escaping the methylation of the enhancer." (PMID 34449663, 2021). "In contrast, cells derived from all 33 chronic lymphoblastic leukemia, all 7 non-Hodgkin’s lymphoma, 7 of 8 chronic myeloid leukemia, and 6 of 8 acute lymphoblastic leukemia patients showed no detectable expression of the heparanase RNA." (PMID 25105093, 2014).
acute myocardial infarction (3 papers, 2014 to 2024). Necrosis of the myocardium, as a result of interruption of the blood supply to the area. "Consequently, heparanase levels are markedly increased in the plasma of patients with acute myocardial infarction." (PMID 24465803, 2014).
adenocarcinoma of the esophagus (3 papers, 2021 to 2025). "Furthermore, Heparanase, an enzyme linked to shedding of the glycocalyx, appears to be upregulated in Barrett‘s esophagus, a precursor of adenocarcinoma of the esophagus." (PMID 40943808, 2025). "For example, HPSE has been identified as the driver of the transition from Barrett’s esophagus to esophageal adenocarcinoma." (PMID 41301515, 2025).
Alzheimer disease (3 papers, 2012 to 2021). A progressive, neurodegenerative disease characterized by loss of function and death of nerve cells in several areas of the brain leading to loss of cognitive function such as memory and language. "Our data indicate that intact heparan sulfate chains are required at multiple sites to mediate neuroinflammatory responses, and further point to heparanase as a modulator of this process, with potential implications for Alzheimer’s disease." (PMID 22692572, 2012).
bacterial sepsis (3 papers, 2022 to 2025). "The aim of this translational study was to investigate the role of the eGC-degrading enzyme heparanase (HPSE), which is known to play a central role in the destruction of the eGC in bacterial sepsis." (PMID 35757776, 2022). "In bacterial sepsis, the potential of HPSE and eGC as future pharmacological targets has already been highlighted." (PMID 35757776, 2022). "At least in bacterial sepsis, the final common pathway of eGC damage appears to be remarkably consistent: the activation and release of the heparan sulfate (HS)-degrading enzyme heparanase (HPSE)." (PMID 35757776, 2022).
chronic pancreatitis (3 papers, 2002 to 2021). A chronic inflammatory process causing damage and fibrosis of the pancreatic parenchyma. "Heparanase was shown to be moderately expressed in chronic pancreatitis." (PMID 11953884, 2002). "Thus, heparanase inhibitors may turn even more important for chronic pancreatitis, protecting beta cell islets from destructive heparanase produced by pancreatic acinar cells and/or inflammatory cells." (PMID 28386074, 2017).
coagulopathy (3 papers, 2021 to 2025). "Interestingly, up-regulation of HPSE in SARS-CoV-2 infection could the potential cause for development of coagulopathy and fatal complications." (PMID 36705773, 2023). "Moreover, growing evidence suggests that heparanase may contribute to heatstroke-induced coagulopathy by causing endothelial damage and glycocalyx degradation, which enhances tissue factor (TF) exposure, promotes prothrombin activation, and leads to excessive coagulation activation." (PMID 40626023, 2025).
esophageal cancer (3 papers, 2014 to 2022). A primary or metastatic malignant neoplasm involving the esophagus. "Kaplan–Meier curves showed that the overall survival time of patients with low HPSE expression in esophageal cancer tissues was shorter than that of those with high HPSE expression (log-rank test, p = 0.047)." (PMID 35840985, 2022). "However, a decreased HPSE expression was found in colorectal, head and neck, and esophageal cancers." (PMID 34461608, 2021).
head and neck squamous cell carcinoma (3 papers, 2014 to 2015). A squamous cell carcinoma that arises from any of the following anatomic sites: lip and oral cavity, nasal cavity, paranasal sinuses, pharynx, larynx, and salivary glands. "Strong heparanase expression in primary tumors and lymph nodes was initially reported to be associated with prolonged disease-free progression in head and neck squamous cell carcinoma, HNSCC." (PMID 25105093, 2014). "The HPV16 oncogene E6 is capable of inducing overexpression of heparanase in head and neck squamous cell carcinoma in vitro, which can be suppressed by radiation in a dose-dependent manner." (PMID 26052253, 2015).
invasive breast carcinoma (3 papers, 2013 to 2021). A carcinoma that infiltrates the breast parenchyma. "The aim of the study was to evaluate the heparanase concentration of invasive breast cancer (IBrC) patients, before and after cancer adjuvant treatment." (PMID 34070058, 2021). "In the present study, we hypothesised that surgical procedures and standard adjuvant therapies influence the change in heparanase concentration of patients with unilateral, invasive breast cancer." (PMID 34070058, 2021).
lupus nephritis (3 papers, 2017 to 2025). Glomerulonephritis in the context of systemic lupus erythematosus. "The heparanase activity in granulocytes of patients with lupus nephritis was higher than heparanase activity in granulocytes in the control group (p = 0.02)." (PMID 27091112, 2017). "The heparanase activity in granulocytes of patients with lupus nephritis class IV was also higher than heparanase activity in granulocytes in the control group (p < 0.05)." (PMID 27091112, 2017). "Correlations between heparanase activity in urine and dsDNA antibodies (r = −0.51; p = 0.04), and between heparanase in urine and hemolytic activity of the complement (r = −0.57; p = 0.03) in the lupus nephritis group were found." (PMID 27091112, 2017). "The connections of the urine heparanase activity with dsDNA antibodies and hemolytic activity of complement suggest that heparanase may be a useful indicator of lupus nephritis immunological activity." (PMID 27091112, 2017).
mesothelioma (3 papers, 2018 to 2024). A usually malignant and aggressive neoplasm of the mesothelium which is often associated with exposure to asbestos. "We have previously demonstrated a profound effect of PG545 in mesothelioma models, further supporting the involvement of heparanase in the pathogenesis of mesothelioma." (PMID 38334603, 2024). "Heparanase appears to orchestrate tumor microenvironment crosstalk that drives mesothelioma tumor progression and poor patient outcomes." (PMID 38334603, 2024). "We found that mesothelioma tumor growth was markedly attenuated by heparanase gene silencing and by heparanase inhibitors." (PMID 30627323, 2018). "A recent publication in the Journal of the National Cancer Institute (JNCI) elucidated a novel molecular pathway that promotes mesothelioma growth by the enzyme heparanase." (PMID 30627323, 2018). "It appears that heparanase secreted by tumor and/or host cells primes the tumor microenvironment to better support mesothelioma tumor growth and drug resistance." (PMID 30627323, 2018). "Notably, the heparanase inhibitors pixatimod (PG545) and defibrotide appeared more effective than cisplatin, a common chemotherapeutics in mesothelioma, in restraining tumor growth, closely associating with a profoundly prolonged survival of mesothelioma-bearing mice." (PMID 35069219, 2021). "Applying pre-clinical and clinical models of human mesothelioma and potent inhibitors of heparanase enzymatic activity (PG545, Defibrotide) we investigated the significance of heparanase in the pathogenesis of mesothelioma." (PMID 30627323, 2018). "Mesothelioma tumors express high levels of heparanase and exhibit high sensitivity to treatment with heparanase-inhibiting compounds, providing a strong rationale for exploring the effect of compound XII on mesothelioma progression." (PMID 38334603, 2024).
non-small cell lung carcinoma (3 papers, 2014 to 2018). A group of at least three distinct histological types of lung cancer, including non-small cell squamous cell carcinoma, adenocarcinoma, and large cell carcinoma. "Recent studies have identified the overexpression of heparanase in non-small cell lung cancer (NSCLC)." (PMID 25105093, 2014). "In addition, treatment with PG545 was associated with reduced phosphorylation levels of Erk (second panel), a most important determinant in non-small cell lung cancer, and in agreement with a connection between heparanase and Erk phosphorylation reported in other settings." (PMID 29721203, 2018).
Osteochondroma (3 papers, 2017 to 2021). A common, benign cartiliginous neoplasm arising from the metaphysis of bone. "HPSE was also detected and found to be widespread in the cartilaginous cap of osteochondromas, whereas, in normal growth plate cartilage, it appeared to be restricted to the hypertrophic zone and perichondrium." (PMID 30544937, 2018). "Possible therapeutic targets have emerged from previous studies, one example being heparanase that we and others found to be up-regulated in human and mouse osteochondromas, but no study has tested efficacy." (PMID 28445472, 2017).
renal cell carcinoma (3 papers, 2012 to 2019). "Finally, a cohort of renal cell carcinoma specimens was examined for both T5 and heparanase mRNA and were immunostained with a mAb that preferentially recognizes T5 over heparanase." (PMID 31850210, 2019). "Heparanase and glycosaminoglycans can modulate initial events of renal cell carcinoma development." (PMID 25549223, 2014).
ulcerative colitis (3 papers, 2013 to 2021). An inflammatory bowel disease involving the mucosal surface of the large intestine and rectum. "It has recently been shown that heparanase is involved in the chronic inflammatory response in ulcerative colitis and chronic inflammation is known to have a profound effect on tumour progression." (PMID 26039697, 2015). "LMWH has been shown to be efficacious in ulcerative colitis and Crohn's disease patients by inhibiting the activity of heparanase." (PMID 23874391, 2013).
acute leukemia (2 papers, 2012 to 2014). A clonal (malignant) hematopoietic disorder with an acute onset, affecting the bone marrow and the peripheral blood. "Thus, apart from the ability of heparanase to increase Xa levels in normal human plasma, a statistically significant positive correlation was found in patients with acute leukemia and healthy donors between the plasma levels of heparanase and Xa." (PMID 23908827, 2012).
acute myeloid leukemia (2 papers, 2012 to 2014). Acute myeloid leukemia (AML) is a group of neoplasms arising from precursor cells committed to the myeloid cell-line differentiation. "In mononuclear cells derived from various leukemias, heparanase mRNA was expressed in 14 of 15 acute myeloid leukemia (AML) samples." (PMID 25105093, 2014).
allergic disease (2 papers, 2015 to 2025). An immune response that occurs following re-exposure to an innocuous antigen, and that requires the presence of existing antibodies against that antigen. "Studies have also observed that the deficiency of HPSE reduces dendritic cell numbers in the lungs and selectively eliminates Th2 cell-mediated immune responses that induce asthma, providing potential new therapeutic targets for anti-inflammatory drugs to treat asthma and other allergic diseases." (PMID 40443529, 2025). "Thus, it is established that heparanase contributes to allergen-induced eosinophil recruitment to the lung and could provide a novel therapeutic target for the development of anti-inflammatory drugs for the treatment of asthma and other allergic diseases." (PMID 26039697, 2015).
bladder pain syndrome (2 papers, 2025). "We found that heparanase 1 (HPSE) and syndecan-1 (SDC-1), syndecan-2 (SDC-2) and syndecan-4 (SDC-4) within the SDC family were up-regulated in the interstitial cystitis/bladder pain syndrome (IC/BPS) tissues." (PMID 40408331, 2025).
chronic allograft nephropathy (2 papers, 2013 to 2021). "Additionally, heparanase, an enzyme recently associated with the progression of chronic allograft nephropathy, could contribute to activate this machinery in renal cells." (PMID 24256696, 2013). "Similarly, IRI induces a long-term over-expression of heparanase by the kidneys, following the initial insult, which is compatible with the establishment of chronic allograft nephropathy in kidney transplantation." (PMID 33671524, 2021).
chronic obstructive pulmonary disease (2 papers, 2015 to 2023). A chronic and progressive lung disorder characterized by the loss of elasticity of the bronchial tree and the air sacs, destruction of the air sacs wall, thickening of the bronchial wall, and mucous accumulation in the bronchial tree. "It is further to mention that the pathophysiological condition of chronic obstructive pulmonary disease was reported to be accompanied by elevated endogenous heparanase expression." (PMID 37386200, 2023). "Examination of lung specimens from patients with different severity of chronic obstructive pulmonary disease (COPD) found increased heparanase expression." (PMID 26039697, 2015).
experimental autoimmune encephalomyelitis (2 papers, 2014 to 2024). An autoimmune demyelinating disease of the central nervous system that is produced experimentally in animals by the injection of homogenized brain or spinal cord in Freund's adjuvant. "HPSE-/- Treg have impaired stability and function in vivo, including in the experimental autoimmune encephalomyelitis (EAE) mouse model of multiple sclerosis." (PMID 38378682, 2024).
fatty liver (2 papers, 2013 to 2022). "The enzyme heparanase has been implicated in liver steatosis." (PMID 35329997, 2022). "Studies in liver tissue revealed that SST0001 significantly decreased liver cholesterol and TG content, and decreased cholesterol and TG uptake by MPMs, an additional mechanism by which heparanase inhibition attenuates liver steatosis." (PMID 35329997, 2022). "Heparanase inhibitors restored liver tissue and maintained normal liver architecture in comparison to the control group, in which marked hepatic steatosis had developed." (PMID 35329997, 2022). "Thus, heparanase inhibition prevents the destructive effect of OS in the liver and contributes to decreasing liver steatosis and fibrosis." (PMID 35329997, 2022). "Herein, we investigated the effect of heparanase inhibition on liver steatosis in E0 mice." (PMID 35329997, 2022). "In summary, our data demonstrate that heparanase inhibition resulted in both decreased lipid uptake by liver cells and decreased lipid oxidation, leading to a significant reduction in the development of liver steatosis." (PMID 35329997, 2022). "Therefore, we investigated herein the effect of heparanase inhibition on the development of liver steatosis and fibrosis in E0 mice placed on HFD, focusing on possible mechanisms by which heparanase inhibition exerts these effects." (PMID 35329997, 2022).